INS (insulin)
Diseases named in the same sentence as INS in open-access papers (continued):
Sharing a sentence is not in itself a finding about the gene and the disease.
Obesity (continued). "The diet-induced restoration of DNA methylation improved body weight and insulin sensitivity in the agouti mouse model, establishing the relationship between obesity and environmental-induced epigenetic changes." (PMID 35163268, 2022). "Obesity, decreased GLUT4 translocation or impairments in signal transduction of muscle and other target cells can cause cellular insulin resistance so agents that promote glucose uptake are desirable as antidiabetic drugs." (PMID 35239729, 2022). "It stimulated glycolysis, improved insulin secretion, and inhibited gluconeogenesis and adipogenesis to treat obesity." (PMID 36263142, 2022). "Vitamin D reduces obesity, thereby indirectly increasing insulin sensitivity by improving muscle mass." (PMID 36079784, 2022). "In the pediatric and adult population, adipose tissue-related inflammation leads to increased circulating neutrophils and monocytes suggesting that obesity alters leukocyte production and/or turnover resulting in abnormal insulin signaling." (PMID 36292751, 2022). "GLP-1RAs stimulate insulin secretion, decrease glucagon concentration, delay gastric emptying, and decrease appetite, making them an attractive therapy for both obesity and T2DM." (PMID 36387846, 2022). "Metabolic effects of obesity include deranged insulin signaling, increased steroid hormone signaling, increased glucose utilization, fatty acid utilization, and aberrant adipokine signaling." (PMID 35326592, 2022). "Endotoxemia exacerbates the inflammatory status of subjects with obesity, further impairing insulin signaling and systemic metabolism." (PMID 36033972, 2022). "Obesity alters insulin and insulin growth factor signaling, putting the body into a chronic inflammatory state and altering sex hormone metabolism." (PMID 35892729, 2022). "Macrophage cytokine production can directly promote adipocyte lipolysis and impair insulin signaling in obesity, which suggests a local mechanism by which weight cycling impairs glucose tolerance." (PMID 36713396, 2022). "Although a 10–20% reduction in weight can have significant metabolic improvements with improved glucose and insulin levels, effects on the chronic inflammatory state of obesity have been less thoroughly investigated." (PMID 35276970, 2022). "Mediated by the cyclin-dependent kinase 5 (CDK5), phosphorylation of PPARγ can significantly reduce insulin sensitivity and induce obesity." (PMID 36551260, 2022). "As expected, fasting-glycaemia, insulin-sensitivity, levels of exercise- and obesity-induced cytokines were ameliorated after 4 months." (PMID 35120179, 2022). "The transgene overexpression of ARRB1 inhibited diet-induced obesity and improved glucose tolerance and systemic insulin sensitivity." (PMID 35159307, 2022). "The extent to which obesity impairs protein synthesis in muscle secondary to reduced insulin-stimulated muscle blood flow requires further investigation." (PMID 35350688, 2022). "Regarding visfatin, an adipokine with arguably insulin-mimetic effects and which is highly expressed in visceral fat appears to be upregulated in patients with obesity and type 2 diabetes mellitus." (PMID 36466401, 2022). "Obesity-induced downregulation of CIDEC is more pronounced in VAT than SAT, and weight loss surgery restores CIDEC expression levels and improves insulin sensitivity in humans." (PMID 35963433, 2022). "Studies performed in rodent models have also shown that inhibition of SCD1 improved insulin sensitivity and prevented diet-induced obesity." (PMID 36992761, 2022). "Here, we demonstrate an important role for insulin in altering airway sensory innervation, leading to obesity-related airway hyperreactivity." (PMID 36107629, 2022). "Accordingly, hepatic insulin clearance and insulin sensitivity were restored in diet-induced mouse models of obesity undergoing Vertical Sleeve Gastrectomy in parallel to inducing the expression of CEACAM1 and IDE, and independently of weight loss." (PMID 36009446, 2022).
Obesity (continued). "Obese and overweight patients usually need higher insulin doses for glycemic control, however high insulin doses aggravate obesity, creating a vicious circle." (PMID 35657127, 2022). "Our data demonstrate that high levels of insulin drives obesity-induced airway hyperreactivity by increasing sensory innervation of the airways." (PMID 36107629, 2022). "The satiety findings are consistent with the putative roles of blood glucose and insulin in appetite control and are relevant to obesity." (PMID 35956366, 2022). "Presence of hypertrophic, insulin-resistant adipocytes is one of the main features of WAT in the context of obesity." (PMID 35807797, 2022). "Other survey-style human studies also included the impact that cannabis use had on obesity, as well as insulin resistance." (PMID 35328862, 2022). "Obesity is an important contributor to type 2 diabetes (T2DM) risk, primarily through its adverse effects on insulin sensitivity." (PMID 35662920, 2022). "While central PC1/3 deficiency only mildly and transiently increased body weight development, β cell-specific ablation of PC1/3 induced pronounced obesity in our preclinical mouse models and insulin therapy prevented hyperphagia." (PMID 35963866, 2022). "Insulin resistant individuals suffering from obesity have activated circulating neutrophils, monocytes and T lymphocytes." (PMID 35406000, 2022). "In fact, thermogenic activation of BAT via cold exposure has been demonstrated to increase glucose uptake in BAT and improve whole body insulin sensitivity in patients with obesity or type 2 diabetes." (PMID 34997461, 2022). "VD–CAL contributes to obesity and its comorbidities by influencing inflammation, insulin sensitivity, hormone production, and cell functions." (PMID 35956362, 2022). "Obesity, in turn, affects the duration and quality of sleep, with a decrease in insulin sensitivity, hyperglycemia, and prevalent cardiometabolic risk factors." (PMID 35627333, 2022). "Their importance in reducing diet-induced obesity has been shown by improved insulin signalling and glucose metabolism." (PMID 36430290, 2022). "Methylation changes in candidate genes are associated with growth, circadian clock regulation, immunity, inflammation, appetite control, metabolism, insulin signaling, and obesity or related phenotypes." (PMID 36397166, 2022). "While few connections between L-Glutamine and GH was reported, oral supplementation of glutamine was reported to reduce obesity and improve insulin sensitivity." (PMID 35331172, 2022). "Together with previous reports of WNT4 up-regulation in obesity our observations suggest an adaptive insulin response coordinating β-cells." (PMID 36271049, 2022). "A sedentary lifestyle contributes to obesity via reducing insulin sensitivity, energy metabolism, mitochondrial function, and redox homeostasis." (PMID 35163268, 2022). "Many metabolic processes are perturbed in skeletal muscle cells from individuals with obesity, and increased fatty acid accumulation and metabolites are thought to play a role in dysfunction of cellular insulin signaling and promoting insulin resistance." (PMID 36467688, 2022). "These common metabolic diseases involve disorders in multiple metabolic pathways, including insulin signaling, insulin secretion, glucose utilization, thermogenesis, mitochondrial function, and autophagy and are all related to obesity." (PMID 35057488, 2022). "Low-sugar dairy is important in dietary management as it allows the slow movement of glucose into blood, resulting in a very low rise in blood—glucose, obesity, and insulin levels." (PMID 35159640, 2022). "Our current study clearly demonstrates a central role for hyperinsulinemia and for a direct effect of insulin on airway sensory nerves in obesity-induced hyperreactivity and hyperinnervation." (PMID 36107629, 2022).
Obesity (continued). "Transition of metabolic status from obesity to insulin resistance and T2D is accompanied with changes in glucose, insulin and circulating lipid levels, as well as changes in inflammatory pathways and hormonal alterations." (PMID 36187112, 2022). "The FBN1 gene was significantly correlated with a profile of adiposity, glucose, and insulin metabolism, even after adjusting for age in the obesity-induced T2DM." (PMID 35462799, 2022). "ROS play a direct role in adipogenesis, and oxidative stress modulates several factors involved in obesity, including genetic factors, gut microbiota, insulin action, ghrelin, inflammation, adipokines, leptin, and the hypothalamic axis." (PMID 36290635, 2022). "The deficient SCD-1 activity was reported to contribute to reducing body adiposity, increasing insulin sensitivity, and alleviating diet-induced obesity." (PMID 35406114, 2022). "Lepob/ob mice are homozygous mutants and show obesity, hyperphagia, transient hyperglycemia, glucose intolerance, and elevated plasma insulin." (PMID 35782067, 2022). "IR in obesity and type 2 diabetes is manifested by decreased insulin-stimulated glucose transport and metabolism in adipocytes and skeletal muscle and by impaired suppression of hepatic glucose output." (PMID 36619574, 2022). "The TBC1D1 gene contributes to the development of obesity by regulating skeletal muscle insulin sensitivity." (PMID 35268233, 2022). "The level of FGF-21 was positively correlated with obesity, fasting insulin and TG and negatively with LDL-C." (PMID 36005598, 2022). "- Anti-obesity, anti-hepatic steatosis, insulin sensitizer (↓body weight; ↓adipocyte size of eWAT; ↓serum insulin, glucose, HOMA-IR) in HFHC-feed mice." (PMID 35769384, 2022). "Obesity-induced metabolic alterations drive changes from healthy to dysfunctional adipocytes contributing to systemic chronic inflammation and insulin resistance and determining adipose tissue inability in adapting to exogenous stimuli." (PMID 35214069, 2022). "Obesity disrupts insulin signaling in the skeletal muscle, resulting in decreased glucose disposal, a condition known as insulin resistance." (PMID 36547071, 2022). "Insulin-stimulated phosphorylations of INSR, IRS-1, Akt2, and GSK3β were markedly reduced in the liver of HFD-fed mice, indicating that HFD-induced obesity impaired hepatic insulin signaling." (PMID 35328400, 2022). "Obesity in T1D is problematic because individuals with obesity progress faster to T1D, have reduced insulin sensitivity compared to their lean counterparts, and have higher risk of complications." (PMID 35873174, 2022). "We end with a clear perspective based on the findings from several recent studies that simultaneously assessed the effects of obesity, insulin sensitivity, and T2D on plasma insulin clearance and help explain the data from smaller earlier studies." (PMID 35054781, 2022). "Previously, differences between sexes contribute to variation in the obesity-related traits such as levels of fasting glucose and insulin were described." (PMID 35627568, 2022). "The failure of the insulin signalling reduces the glucose absorption by the cell, leading to the onset of T2D, obesity and GDM in pregnant individuals." (PMID 36078079, 2022). "These cells are abundant in the visceral adipose tissue of normal diet mice, but their proportion is greatly reduced in insulin-resistant animal models of obesity." (PMID 36248854, 2022). "In this study, we revealed that MKP-2 expression was upregulated in liver tissue in humans with obesity and fatty liver disease and in insulin-responsive tissues in mice with obesity." (PMID 35745205, 2022). "A possible correlation between MCP-1 concentrations and obesity related measures (body fat percentage (BF%), insulin sensitivity and cytokine expression) were investigated in another population of 73 healthy, lean to obese, neutered domestic short-haired cats." (PMID 36064726, 2022).
Obesity (continued). "Recently, it was found that in early obesity mice, hepatocytes secreted miR-3075-enriched EVs to improve insulin sensitivity." (PMID 35770186, 2022). "MiR-4643 positively correlated with obesity markers (hip and BMI) and insulin levels, and negatively with urea." (PMID 35807162, 2022). "At the same time, PPARγ is related to the regulation of obesity factors, such as ADPN and LEP; changes in obesity factors are the best predictors of insulin sensitivity." (PMID 35407014, 2022). "This bacteria has been shown to improve insulin sensitivity and prevent obesity in mice, but its role in the development of MI needs further investigation." (PMID 36620030, 2022). "Second, we applied a preventive strategy to investigate the effect of insulin-sensitizing drugs in the context of obesity and T2D." (PMID 36103974, 2022). "Other studies in animal models of obesity and T2D reported a downregulation of PINK associated with mitophagy impairment, showing a link between mitochondrial quality control and insulin sensitivity." (PMID 35741464, 2022). "It has been reported that obesity leads to changes in the metabolic state of skeletal muscle cells including reduced insulin-mediated glucose uptake, oxidative metabolism, and lipid oxidative capacity [reviewed in]." (PMID 36467688, 2022). "Many studies consistently supported dietary PCs with health benefits in murine models and humans; for example, anti-obesity, improve insulin sensitivity." (PMID 36145094, 2022). "In conditions such as IGT, T2DM or obesity, insulin-stimulated rates of blood flow in adipose tissue and muscle are severely impaired." (PMID 35215472, 2022). "These pellets have a statistically significant (p<0.05) impact on obesity biomarkers by increasing adiponectin and decreasing leptin, free fatty acid and insulin concentrations relative to HFD control." (PMID 35910274, 2022). "The hypothalamic CBS (cystathionin-β-synthase)/H2S pathway reduces obesity and improves insulin sensitivity through brain–adipose interactions." (PMID 35743160, 2022). "Recent study showed caspase induction and Bcl-2 inhibition for altering insulin signaling in human adipose tissue to prevent obesity." (PMID 36263142, 2022). "The expression of insulin and Pc2 was significantly induced in the islets of obese β-Xbp1+/+Ob mice compared with lean β-Xbp1+/+Wt mice, providing evidence of an improved beta cell capacity to meet greater insulin demand in obesity." (PMID 35316840, 2022). "Adiponectin is an essential adipokine in obesity and psoriasis since it promotes fatty acid oxidation and improves insulin sensitivity." (PMID 35886846, 2022). "A previous study observed that the levels of this adipokine reached the highest values at the disease phase when plasma insulin levels and obesity peaked, whereas, with progression of T2D, levels of vaspin decreased." (PMID 36289764, 2022). "In this study, we first observed that MGE treatment can alleviate obesity by inhibiting body weight gain and fat accumulation in adipose tissues and liver, improving insulin and glucose sensibilities in DIO mice." (PMID 35769373, 2022). "Decreased sensitivity for insulin-mediated glucose uptake in skeletal muscle is a core pathophysiological denominator in obesity-related alterations in metabolic phenotype." (PMID 35055038, 2022). "For three subjects from the group with obesity, some clinical data were missing including p-insulin, 120 min p-glucose, HOMA-IR and BMI." (PMID 36340033, 2022). "Studies have shown that the key targets of acupuncture to improve obesity are mainly neurons or neuropeptides in the hypothalamic arcuate nucleus and peripheral hormones (leptin and insulin)." (PMID 36248406, 2022). "The current results extend previous findings relating insulin resistance and exercise resistance to their relationship with obesity as well." (PMID 33897458, 2021).
Obesity (continued). "For example, a 12-week diet and exercise intervention induced weight and fat loss, and improved blood lipids, fasting insulin and HOMA-IR in children (range: 6–11 years) with obesity." (PMID 34095194, 2021). "In prediabetes metabolic states such as obesity and glucose intolerance, β-cells biosynthesize and secrete more insulin in response to increased blood glucose level." (PMID 34673835, 2021). "For example, this neuropeptide has a stimulative effect on insulin secretion from isolated rat islets and decreases insulin level in blood in mice with diet-induced obesity." (PMID 34681728, 2021). "Xu and collaborators demonstrated that miR-26a was capable of preventing obesity-induced metabolic abnormalities in the liver, and insulin resistance locally and distally." (PMID 34440850, 2021). "We recently reported that APs contribute to adipogenesis during the progression of obesity and M2 macrophages enhance adipogenesis through the recruitment of APs to preserver systemic insulin sensitivity." (PMID 34959926, 2021). "Various serum factors in the blood of subjects with obesity induce inflammation and oxidative stress through various mechanisms and can negatively affect insulin signaling." (PMID 33579000, 2021). "In contrast, in obesity, partial reduction of plasma leptin levels has been suggested to enhance insulin sensitivity." (PMID 34682732, 2021). "Knockdown of CTRP6 promotes brown adipogenesis, insulin sensitivity and attenuates diet-induced obesity via the p38MAPK/Hh signalling pathway in conjunction with the upregulation of brown fat markers and mitochondrial metabolic factors." (PMID 33938394, 2021). "On the other hand, the sensitivity of antilipolysis and thereby insulin sensitivity of fatty acid handling (Adipo-IR) is clearly reduced in obesity but fully normalized in the post-obese state." (PMID 34321614, 2021). "We analyzed this new mouse model using molecular profiling, whole mount three-dimensional tissue imaging, tissue respiration, and glucose and insulin tolerance tests in models of diet-induced obesity." (PMID 33220490, 2021). "These bile acids have signaling properties, and interestingly post-bariatric surgery insulin sensitization in individuals with obesity can be mediated by alterations in microbial bile acid metabolite FXR signaling." (PMID 33972511, 2021). "As a consequence of obesity, the levels of adiponectin, a marker of insulin sensitivity, were decreased, while leptin, as expected, was increased in the obese mice." (PMID 35008488, 2021). "In recent years, the link between the obesity and the subsequent leptin and insulin impaired signals with the onset of the AD pathology have been studied." (PMID 34575083, 2021). "Third, our data also lack information of the SRA1 and SRA protein (SRAP) expression in main insulin target tissues other than white subcutaneous adipose tissue in obesity." (PMID 34685582, 2021). "Elevations of circulating branched-chain amino acids (BCAA) are observed in humans with obesity and metabolic comorbidities, such as insulin resistance." (PMID 34525937, 2021). "In mouse model, it has been demonstrated that over expression of VEGFA in adipose tissue provide protection against high fat diet induced obesity and insulin sensitivity." (PMID 34429108, 2021). "Overall obesity rate was 40.4% in the insulin dependent and 16.1% in the insulin independent diet group (p < 0.01)." (PMID 34640439, 2021). "RAGE appears to be involved in the progression of obesity, correlating with adipose tissue inflammation, adipocyte hypertrophy, and insulin sensitivity." (PMID 34686659, 2021). "We reviewed the obesity-related kidney disease regarding the involved pathophysiologic mechanisms that include the hemodynamic, the adipose tissue-related and the insulin resistance—hyperinsulinemia pathways." (PMID 33928108, 2021).